MMP9 (matrix metallopeptidase 9)
Diseases named in the same sentence as MMP9 in open-access papers (continued):
Sharing a sentence is not in itself a finding about the gene and the disease.
tumor (continued). "On the other hand, MMP-2-positive staining was only found in the tumor-like cells (enlarged photograph of black frame) and their staining densities were lighter than those of the areas of MMP-9-positive staining." (PMID 37175975, 2023). "Snail has previously been shown to induce the transcription and expression of matrix metalloproteinase-9 (MMP-9) and is linked to epithelial–mesenchymal transition (EMT) and neovascularization in the tumor microenvironment (TME)." (PMID 37190108, 2023). "For this reason, the combined use of MMP9 with other tumor markers such as CA-125 has been recommended for the diagnosis of CC." (PMID 36831674, 2023). "The increased expression of MMP9 is indicative of tumour progression through angiogenesis, invasion and metastasis, and it also causes the epithelial-mesenchymal transition, which shortens survival." (PMID 37543674, 2023). "Inhibition of MMP-9/gelatinase B reduced PCa invasion in vitro and tumor growth, invasion, and angiogenesis in vivo." (PMID 37025604, 2023). "Of additional interest, the MMP-9 promoter activity of HNSCC tumor cells in adherent 2D cell culture is fundamentally different from that in 3D spheroid culture." (PMID 36674806, 2023). "Matrix metalloproteinase 9 (MMP9) is involved in the tumor cells’ metastatic invasion as a downstream EMT transcription factor." (PMID 36937833, 2023). "The co-treatment group significantly downregulated the CD31 and MMP9 expression in the tumor tissues when compared to the DOX or CPPS-II treatment groups individually." (PMID 37375842, 2023). "MMP-2 (gelatinase A) and MMP-9 (gelatinase B) are related to tumor invasion and metastasis by their special capacity to degrade the type IV collagen found in basement membranes." (PMID 37108185, 2023). "Our results showed that pro-inflammatory and tumor-promoting factors MMP9, IL-8, OSM, IL-1β, TNF-α, CXCL3, and ROS all increased to varying degrees after OCOs stimulation." (PMID 37644468, 2023). "The combination of CA4-NPs with MMP9-DOX-NPs showed significant antitumor efficacy in situ in 4T1 tumor-bearing mouse models." (PMID 37111692, 2023). "There was a significant increase in the serum levels of MMP-9 among the tumor stages and nodal involvement with a significant p-value of 0.002 and 0.001." (PMID 36938194, 2023). "By releasing angiogenic factors including S100A8 and S100A9, as well as activating vascular endothelial growth factors A (VEGFA) in the extracellular matrix and MMP9, tumor angiogenesis was maintained by neutrophils." (PMID 36609243, 2023). "In summary, our data suggest that the direct interaction of HNSCC cells and BMSCs promotes tumor progression by significantly facilitating angiogenesis via MMP-9 expression." (PMID 36674806, 2023). "NETs contain proteins including matrix metallopeptidase-9 (MMP-9) and histonectin G that promote tumor growth." (PMID 37007004, 2023). "Previous studies on COS’s impact on MDA-MB-231 cells reported that COS reduced matrix metalloproteinase-9 (MMP-9) secretion, thereby inhibiting tumor cell migration and invasion." (PMID 38248651, 2023). "Cathepsin K (encoded by CTSK), a lysosomal cysteine proteinase involved in bone remodeling and tumor invasiveness, is known to cleave and activate MMP9 in tumors." (PMID 38123589, 2023). "The genes that showed increased expression in tumours were FN1, COL1A1 and MMP9 (p value < 0.05), which can be considered high-risk genes to indicate the prognosis level of patients with COAD." (PMID 37543674, 2023). "Other ligands, such as CXCL12 and MMP9, have documented roles in invasion in other tumor types, but their role in PDAC invasion remains to be explored in depth." (PMID 36881486, 2023). "Anti-tumor treatment suppressed properties of LCSLCs, inhibited expression of stemness markers, and also reduced MMP-9 activity." (PMID 37766868, 2023).
tumor (continued). "Similar results were obtained by analyzing the association between the expression of the studied genes in tumor samples and patient survival (TIMP1, p = 0.5972; MMP2, p = 0.9627; MMP9, p = 0.8563)." (PMID 37509417, 2023). "Tumor cells secrete critical molecules called pro-angiogenic factors, such as VEGF and matrix metalloproteinase (MMP)-9, to drive tumor-induced neovascularization." (PMID 37375411, 2023). "MMP-2 and MMP-9 are two important matrix metalloproteases expressed in tumor cells, which promote carcinogenesis by destroying the extracellular matrix type IV collagen at the basement membrane during cancer invasion and metastasis." (PMID 37259418, 2023). "Strikingly, monocytes increased vessel permeability by disrupting EC junctions and secreted MMP9 to disrupt the vascular barrier, promoting tumor extravasation." (PMID 37064144, 2023). "Meanwhile, the results of immune-histochemical staining showed that MMP-2 and MMP-9 were abundantly expressed in the left atrium tumor-like lesions of αMHC-Cre mice." (PMID 36834504, 2023). "More studies should further investigate the relationship between ESR1 and MMP9 in the pathogenesis of uLMS, but it is possible that these two genes, alone or combined, have an influence on tumor behavior." (PMID 37373974, 2023). "Herein, we reported, for the first time, that ESM1 activates the downstream MAPK pathway by binding to the membrane receptor c-Met on the surface of HUVEC cells to promote the production of HIF1α, VEGFA, and MMP9, eventually promoting tumor angiogenesis." (PMID 38201620, 2023). "From our data, emodin modulated the TME in both tumor-bearing pancreas tissue (suppressing NF-κB and MMP-9) and metastasis-bearing hepatic tissue (increasing E-cadherin) in pancreas and splenic injection models, respectively." (PMID 37444525, 2023). "Correspondingly, the overexpression of matrix metalloproteinases (MMPs), including MMP-2 and MMP-9, was shown as principal mediators of tumor invasion and metastasis where decomposition of the extracellular matrix is critical for tumor progression." (PMID 36910721, 2023). "The peritumoral administration of LL-37 significantly increased the expression of CXCL5, IL23A, MMP1a, and MMP9 mRNA in the tumor microenvironment." (PMID 36980564, 2023). "It is expressed in invasive tumors and highly involved in tumor progression, whereas in normal cells, MMP-9 expression is negligible." (PMID 36674806, 2023). "As demonstrated in tumor cells during angiogenesis, CD44 mediates cell surface localization of MMP9 and MMP2 and is thereby also implicated in TGF-β1 activation." (PMID 37894778, 2023). "Studies have shown that β-catenin signaling pathway can promote proliferation and metastasis of tumor cells by activating the transcription of various oncogenes, such as MMP9, C-myc, and CDK4." (PMID 37460940, 2023). "In spheroids, the presence of BMSCs appears to play a major role in downregulating the MMP-9 promoter in the tumor cells." (PMID 36674806, 2023). "ADCC triggers the release of ROS in addition to other cytotoxic molecules such as lactoferrin, elastase, arginase, myeloperoxidase, cathepsins, defensins, and MMP9 to eliminate tumor cells." (PMID 37376417, 2023). "MMP-9 had a statistically significant higher level in tumor tissues than non-tumor tissues in PTC (p < 0.05)." (PMID 37175113, 2023). "Nanoparticle-mediated delivery of LGALS3BP exhibited anti-metastatic and antitumor effects, reducing TAK1 phosphorylation and MMP9 expression in TNBC primary tumor tissues." (PMID 37041137, 2023). "Intriguingly, silencing of Psf2 decreases the expression of matrix metallopeptidase 9, which is necessary for tumor invasion, hence suppress tumor cell migration and invasion." (PMID 36776764, 2023). "N-cadherin and matrix metalloproteinase-9 (MMP9) expression levels were markedly reduced in all tumor tissues in the shGIPC1 group, as compared to those in the shControl and rescue groups." (PMID 38186571, 2023).
tumor (continued). "MMP-9 can increase tumor cell invasion and metastasis and promote vascular endothelial cell migration to form new blood vessels through the degradation of the extracellular matrix and basement membrane." (PMID 36880008, 2023). "As MMP-2 and MMP-9 expressed in most all human cancers with a key role in degrading ECM and involving in tumor progression and metastasis, we inspected the expression level of MMP-2 and MMP-9 in the atrium with tumor-like growth." (PMID 36834504, 2023). "COMP can enhance the ability of tumor cells to degrade ECM by upregulating the expression of MMP9, thereby, promoting EMT, which in turn promotes tumor invasion and metastasis." (PMID 37229458, 2023). "Overexpression of MMP2/MMP9 after incubation of recipient tumor cells with sEVs from irradiated donor cells is considered one of the main mechanisms of the non-target effects of radiotherapy." (PMID 37109070, 2023). "We evaluated expression levels of key factors CCL-2, RANKL and MMP-9 and found higher expression of RANKL and MMP-9 in tumor tissue compared to normal breast tissue." (PMID 36890825, 2023). "MDSC can also participate in tumour angiogenesis by mediating the migration of endothelial progenitor cells in the circulatory system through the secretion of MMP-9." (PMID 37742025, 2023). "By causing monocytes to secrete the matrix metalloproteinase 9 (MMP9) enzyme, CCL2 and CCL3 can promote the extravasation of tumor cells." (PMID 37373025, 2023). "EGCG downregulated the expression of NF-κB and MMP9 in both protein and mRNA levels in the tumor and SW780 cells." (PMID 36677584, 2023). "Matrix metallopeptidase 9 (MMP9) and matrix metallopeptidase 2 (MMP2) are the most frequent metalloproteases associated with tumor angiogenesis." (PMID 37968257, 2023). "Morphine, an opiate, has been shown to impact tumor progression from its effects on MMP-9 expression and increase NO production." (PMID 36831374, 2023). "The matrix metalloproteinases (MMPs), especially MMP-2 and MMP-9, can degrade extracellular matrix components, which are closely related to the tumor migration and metastasis." (PMID 37221457, 2023). "It has been proven that molecular insights of MMP-9 provide a better understanding of the pathophysiology of tumor invasion and metastasis." (PMID 36837539, 2023). "Further analysis revealed that MMP-9 was predominantly localized in the tumor stroma and surrounding blood vessels." (PMID 38089632, 2023). "MGF causes downregulation of matrix metallopeptidase 2 (MMP‐2) and matrix metallopeptidase 9 (MMP‐9), which result in decreased cellular proliferation (progression) and tumor motility; these processes ultimately lead to an increase in body weight." (PMID 38455223, 2023). "MMP-9 had a statistically significant higher level in tumor tissues than non-tumor tissues in PTC (p < 0.001)." (PMID 37175113, 2023). "In particular, high levels of MMP-9 and MMP-2 were found to be associated with a higher tumor grade, a lesser response to chemotherapy, and a worse survival outcome." (PMID 36980765, 2023). "MIH promotes the anti-tumor effect of RT via Bax-mediated cell death, enhances the immunity of cells undergoing RT, and suppresses the increase in matrix metalloproteinase-9 (MMP-9) expression induced by RT." (PMID 37107299, 2023). "PKD3 also stimulates secretion of multiple tumor-promoting factors including matrix metalloproteinase-9 (MMP-9), interleukin-6 and 8, and growth regulated alpha protein (GROα)." (PMID 36672148, 2023). "LncRNA UCA1 has a high level in PTC consistent with high expression of MMP-9, which is related to tumor stages and lymph node metastasis." (PMID 37175113, 2023). "Patients diagnosed with PTC on account of exposure to the external and internal radiation of the Chernobyl nuclear accident have an abundant expression of MMP-9 in tumor tissues, demonstrating the high aggression of the tumor." (PMID 37175113, 2023).
tumor (continued). "IHC of subcutaneous tumours showed NF-κB/p65 nuclear expression and MMP9 (a marker of invasion and NF-κB target) decreased in the PI16 overexpression group but increased in the PI16 knockdown group." (PMID 37525118, 2023). "MMP2 and MMP9 participate both in the formation of new blood vessels and lymphangiogenesis, enabling adequate blood supply to the tumor, as well as the penetration of cancer cells into blood and lymphatic vessels." (PMID 37509417, 2023). "Formation of new blood vessels requires the angiogenic factor VEGF and its proteolytic release from tumour matrix by MMPs, predominantly by the MMP-9 that is delivered into the tumour microenvironment by tumour-infiltrating leukocytes." (PMID 37446252, 2023). "miR-124 targets many proteins like SCP1, Rho-associated protein kinase 1 (ROCK1), STAT3, matrix metallopeptidase 9 (MMP9), and inhibits tumor cell proliferation in GBM." (PMID 37508353, 2023). "We used IHC to detect the expression of IL-1β and MMP9 in 10 sensitive and 13 resistant tumor tissues from MSI-H/dMMR patients." (PMID 37106440, 2023). "Exosomes and tumor mRNA from primary OC and LN metastatic patients were analyzed for their quantitative gene expression patterns of MMP9, CXCL8, and FN1." (PMID 37640804, 2023). "MMP2 and MMP9 are molecular markers of tumor invasion and metastasis, including GC, and inhibition of their expression reduces the invasion and migration capabilities of GC cells 22-24." (PMID 36778127, 2023). "MMP-2 and MMP-9 belong to the gelatinase class, and in cancer, they play important roles in angiogenesis, tumor growth, invasion, and metastasis." (PMID 38003553, 2023). "Further examination on preoperative GBM samples found a distinct difference between the original tumour and the recurrence based on the MMP-9 level of serum sEVs." (PMID 36765669, 2023). "MMP-2 and MMP-9 activity was also analysed between xenograft tumours derived from “double-hit” and “single-hit” cell lines." (PMID 38203696, 2023). "By inhibiting the expression of MMP-9 metalloproteinase and interleukin-8 (IL-8), the glycosyl dietary flavonoid luteolin (8-C-d-glucopyranoside) inhibits tumor invasion in 12-O-tetradecanoylphorbol-13-acetate (TPA)-treated MCF-7 breast cancer cells." (PMID 37110140, 2023). "Many studies have confirmed that MMP2 and MMP9 are highly expressed in many malignant tumor cells and their stromal components." (PMID 37686118, 2023). "PPAT secrets multiple kinds of cytokine, including IL-6, TNF-ɑ and MMP9, which participates in the development of tumour growth and invasiveness." (PMID 37042512, 2023). "The combined down-regulation of RELA and MMP9 expression upon SHN3 silencing inhibits tumor growth and cancer invasion, supporting a potential therapeutic value for SHN3 targeting in IL13Rα2-positive tumors." (PMID 37963919, 2023). "It is described that the prolonged neutrophil lifespan facilitates the secretion of pro-metastatic factors, such as oncostatin M and MMP-9, which promote the migration of tumor cells." (PMID 38136358, 2023). "In the present study, PCDH10 overexpression significantly decreased the expression of genes associated with tumor progression and metastasis, including EREG, MMP1, MMP9, TGFB1, RASA4, and CXCL8, in GC cells." (PMID 37147733, 2023). "SHN3 silencing caused a potent inhibition in cell invasion and proliferation, associated with a down-regulation of the Wnt/β-catenin pathway, an extensive decline of MMP9 expression and the subsequent inhibition of tumor growth and metastasis in mouse models." (PMID 37963919, 2023). "In summary, ERIANIN acts on the Wnt and ERK1/2 pathways and their downstream genes, MMP-2 and MMP-9, to inhibit tumor metastasis, as shown in." (PMID 37187758, 2023). "Jiang used the sequential delivery of CA4-NPs and matrix metalloproteinase 9 (MMP9) to enhance tumor therapy." (PMID 37111692, 2023).
tumor (continued). "Protein kinase C (PKC) is a ubiquitous family of enzymes involved in several cellular pathways, such as mediating cell growth and tumor invasion by activating MMP-9." (PMID 37958702, 2023). "TGF-β promotes the EMT via the SMAD2/3 pathway, and MMP-9 is a TGF-β target gene that promotes tumor invasion." (PMID 37524814, 2023). "In TC and BC, ERα enhances the migration and invasion of tumor cells by upregulating MMP-9 and downregulating E-cadherin." (PMID 37229458, 2023). "The genes positively associated with NLR [CD39 (ENTPD1), PTEN, MYD88, MMP9 and LDH] have immunosuppression, inflammation and tumor-promoting activity." (PMID 37684649, 2023). "In HCC, abnormal activation of Nrf2 promotes the expression of MMP2 and MMP9, which are matrix metalloproteinases that can degrade the basement membrane and promote tumor migration and invasion." (PMID 37174639, 2023). "Hinokiflavone has been shown to exert potential anti-tumor effects by inhibiting MMP-9 in human-based pharmacophore modeling and kinetic simulations." (PMID 37175435, 2023). "Gingipain proteases produced by P. gingivalis can activate NF-κB and MMP-9, both significant for tumor invasion and metastasis." (PMID 38029267, 2023). "The specificity of CREKA-GK8-QC binding to MMP-9 and fibronectin in the 4T1-tumor-bearing mice was verified through immunofluorescence staining." (PMID 36978072, 2023). "On the other hand, data from 3D and 2D co-culture models indicate opposing regulation of the MMP-9 promoter in tumor cells once stromal cells are involved." (PMID 36674806, 2023). "The LPs degraded in the tumor tissue containing high levels of matrix metalloproteinase-9 (MMP-9) and released PM, THZ, and HY19991 simultaneously." (PMID 37720349, 2023). "In the process of tumor progression, MMP-2 and MMP-9 can mediate the invasion of tumor cells into the basement membrane through the degradation of collagen IV, thus resulting in tumor metastasis and diffusion." (PMID 36906534, 2023). "In BC, MMP-9 specifically degrades type IV collagen in the extracellular matrix while promoting the progression of tumor invasion and metastasis." (PMID 37372062, 2023). "To explore the tumor characteristics in the subcutaneous xenograft model, we conducted IHC staining for CERS1 and the metastasis-associated marker MMP-9 in xenograft tissues." (PMID 37046655, 2023). "The inhibition of MMP-9 and the elicitation of anti-tumor immune response generated by LS further prove it to be a more promising anti-tumor drug." (PMID 37175113, 2023). "P. gingivalis binds to protease activated receptor and cleaves the MMP-9 active form, which subsequently facilitates tumor cell invasion and migration." (PMID 38029267, 2023). "The tumor-suppressive role is thought to prevent tumor invasion by suppressing MMP9 production and activity and MAPK." (PMID 37970212, 2023). "Matrix metalloproteinase-2 (MMP-2)- and MMP-9-sensitive materials respond to the tumor microenvironment by overexpressing MMP-2 and MMP-913." (PMID 37144580, 2023). "Treatment with eptifibatide, an integrin β3 antagonist, not only prevented platelet aggregation but also reduced tumor PAI-1 and MMP-9 expression and interfered with tumor-EC adhesion." (PMID 37064144, 2023). "Transcript/protein pairs enriched in these pathways included inflammatory cytokines such as IL6 and IL8 as well as matrix remodeling enzymes (e.g., MMP9), indicating a tendency towards tumor invasion of the surrounding tissue." (PMID 36732562, 2023). "Since BMP-4and MMP-9 contribute to extracellular matrix remodeling, which isa major component of tumor progression, an increased expression ofthese proteins likely facilitates abnormal ECM-promoting cell migrationin NKX3.1-silenced cells." (PMID 37720744, 2023). "MMP-9 in OSCC increases tumor progression through angiogenesis, degrades the basement membrane, and facilitates metastasis by changes in tissue shape." (PMID 36938194, 2023).